CRP (C-reactive protein)
Diseases named in the same sentence as CRP in open-access papers (continued):
Sharing a sentence is not in itself a finding about the gene and the disease.
cancer (continued). "Inflammation-related parameters, including neutrophil-lymphocyte ratio (NLR), monocyte-lymphocyte ratio (MLR), platelet-lymphocyte ratio (PLR), and C-reactive protein/albumin ratio (CRP/Alb), are associated with tumorigenesis and development and serve as independent prognostic factors for cancer." (PMID 36338698, 2022). "Additionally, ours is the first study to characterize the association between CRP levels and BC risk among Nigerian women, and further to do so by cancer molecular subtype." (PMID 34194621, 2021). "However, when patients who had an underlying cancer were excluded from the analysis and CRP and albumin were combined in the measure of high-grade inflammation, poGPS remained significantly associated with higher 28-day mortality." (PMID 34962922, 2021). "Moreover, increased CRP levels are known to be associated with lymphocytopenia, impaired T cell response within the tumor, and cancer progression." (PMID 33179214, 2021). "Prospective population studies and the literature overall have had mixed findings, but seem to support the ‘induction hypothesis’ that elevated baseline CRP is significantly correlated with a risk for overall cancer development." (PMID 34926085, 2021). "While the molecular mechanism underlying tumor-related CRP elevation in HCC or other cancers remains unknown, several possible mechanisms have been proposed." (PMID 33685417, 2021). "In the univariate analysis, age (p < 0.0001), gender (p = 0.0074), BMI (p = 0.0103), serum albumin (p < 0.0001), total lymphocyte count (p < 0.0001), eGFR (p = 0.0026), CRP (p < 0.0001), and the presence of advanced cancer (p < 0.0001) were significant factors linked to SARC-F ≥4 points." (PMID 34575208, 2021). "However, the risk of cancer in weight loss associated with individual abnormalities, notably a raised C-reactive protein, was sufficient to trigger further investigation for cancer under current NICE guidelines." (PMID 33558706, 2021). "Moreover, when patients who had an underlying cancer were excluded from the analysis, and CRP and albumin were combined in the measure of low-grade inflammation, GPS remained independently associated with higher 6-month mortality." (PMID 34962922, 2021). "Epidemiological studies have suggested that elevated CRP levels in various cancers may be associated with poor prognosis." (PMID 33584142, 2021). "Risk of death increased with higher CRP or ferritin, more severe renal disease and cancer." (PMID 33543243, 2021). "In addition, existing research shows that both pre‐CRP and postoperative CRP (post‐CRP) levels are associated with the prognoses for cancer patients." (PMID 33270989, 2021). "According to an aetiological study at the molecular level, elevated levels of inflammatory factors (e.g., tumour necrosis factor-alpha, interleukins 1 and 6, and C-reactive protein levels) were observed in patients with cancer and were linked to reduced survival." (PMID 34957306, 2021). "C-reactive protein (CRP) is associated with risk and aggressiveness for several types of cancer." (PMID 34194621, 2021). "In addition, elevated CRP levels have been shown to also associate with cancer progression and decreased survival." (PMID 33924623, 2021). "Furthermore, an elevated serum CRP concentration is associated with tumor invasiveness, cancer progression, and a higher recurrence rate in CRC patients." (PMID 34441316, 2021). "Notably, elevated levels of CRP are associated with an overall risk of cancer and the risk of various organ cancers." (PMID 33671768, 2021). "Increasing age at cancer diagnosis was associated with higher CRP in survivors." (PMID 33605556, 2021). "Previous studies have demonstrated that an inflammatory reaction is closely related to the development and progression of malignant tumors, and increase in some inflammatory indexes such as C-reactive protein and neutrophils is associated with poor prognosis of tumors." (PMID 34787725, 2021).
cancer (continued). "Although the exact mechanisms for CRP to be associated with worse prognosis in cancer patients are still unclear, CRP might reflect malignant characteristics of the tumor." (PMID 34350956, 2021). "Measuring preoperative plasma level of CRP might be useful in risk stratification for poor outcome after surgery in older cancer patients." (PMID 33920422, 2021). "Elevated CRP levels have been shown to be associated with increased risk of cancer." (PMID 33924623, 2021). "From a cancer‐immunologic point of view, it would be of high relevance to identify the distinct immune signatures associated with non‐CRP response and IO treatment failure to identify potential targets for tailored combination therapy in this immunotherapy‐unresponsive RCC subgroup." (PMID 34925829, 2021). "When various acute and chronic infections, malignant tumors, trauma, surgical radiation, and other causes of tissue injury occurs the increase of CRP synthesis is related to the acute phase response mediated by cytokines and other media, and is linearly related to the degree of tissue injury." (PMID 35024012, 2021). "However, high levels of CRP were found to be strongly associated with advanced disease severity in numerous cancer types (elaborated below)." (PMID 33324413, 2020). "Whether the circulating level of CRP can play a causal role in the pathogenesis of comorbid cancers in PMR/GCA, or it is simply a marker of occult cancer in this group of patents, is a matter of interest and should be addressed in future research." (PMID 33291857, 2020). "CRP is directly associated with acceleration of angiogenesis, which enhances the progression and metastasis of malignant tumors and contributes to the progression of cancer." (PMID 32676164, 2020). "This hypothesis is supported by the finding that the LRC was found unaffected by higher CRP levels and the decreased OS may therefore be due to non-cancer-associated events." (PMID 32604773, 2020). "Most consistent interpretations of the diagnostic significance of CRP in cancer." (PMID 33324413, 2020). "Hence, CRP measurements have potential utility as a diagnostic tool in assessing disease status and progression, including in cancer." (PMID 33324413, 2020). "One particularly confounding disease in understanding of diagnostic relevance of CRP is cancer." (PMID 33013897, 2020). "Elevated levels of neutrophil counts and CRP may also play a causal role in the pathogenesis of cancer." (PMID 33192519, 2020). "Furthermore, across the quartiles of CRP, individuals in the highest quartile had a significantly higher cancer death risk compared with the first quartile (Q4 = HR: 1.30; 95% CI: 1.16, 1.50)." (PMID 31936330, 2020). "As well, epidemiologic studies suggest that RDW is associated with increased levels of CRP and may be a predictor of chronic diseases and mortality in cardiovascular disease, cancer, and other diseases." (PMID 32027700, 2020). "The authors genotyped almost 19,000 individuals from three population-based prospective cohort studies for 13 CRP-related SNPs that were identified from the genome-wide association study, and found a few positive associations of genetic polymorphisms with cancer risk." (PMID 31936330, 2020). "C-reactive protein (CRP) is a well-established circulating marker of inflammation whose blood levels are positively associated with the risk and prognosis of several types of cancer." (PMID 32477370, 2020). "Some studies have found that PCT and CRP levels are associated with tumor stage and that their levels are higher in patients with advanced tumors than in patients with early-stage cancer." (PMID 32908505, 2020). "In the multivariate analysis evaluating CRP, being female was associated with lower cancer mortality compared to being male in both the NHANES III (HR = 0.68, 95%CI: 0.54–0.87; p = 0.003) and the NHANES 1999–2002 (HR = 0.52, 95%CI: 0.27–0.99; p = 0.047) datasets." (PMID 33243216, 2020).
cancer (continued). "The increased serum CRP in hypernatremic patients may be associated with increased inflammatory responses in cancer patients." (PMID 33552948, 2020). "Second, since not all patients underwent urine tests, chest X-ray examination, computed tomography, etc., we cannot completely exclude infectious diseases and malignant tumors that may have caused the elevated CRP and SAA levels." (PMID 32245401, 2020). "Moreover, high baseline levels and specific single nucleotide polymorphisms of CRP have been previously associated with an increased risk of cancer." (PMID 32974174, 2020). "High CRP levels have been associated with poor survival in a wide variety of cancers." (PMID 33291708, 2020). "In the elderly, elevated CRP is linked to poor physical status and cognitive performance, and individuals with increased inflammatory markers encounter an at least two times higher cancer incidence compared to those with normal values." (PMID 32423000, 2020). "In this line, results from a multinational cohort of patients with advanced cancer (age 54–70 years) reported that elevated levels of C-reactive protein (CRP) were significantly associated with appetite loss, cognitive and physical dysfunction, pain and fatigue." (PMID 31443557, 2019). "Furthermore, it is recognized that an elevated CRP and low albumin concentration are risk factors for the development of cancer." (PMID 31487957, 2019). "Besides, the association between prognosis and CRP levels in patients with cancer is currently well established." (PMID 30923859, 2019). "Higher nut consumption might influence cancer risk through its association with lower circulating levels of total cholesterol, CRP, IL-6, and insulin." (PMID 31409026, 2019). "However, the mechanisms driving the association of CRP, an acute phase reactant protein produced by the liver, with cancer-specific survival are poorly understood." (PMID 31263677, 2019). "The association between CRP levels and cancers has been comprehensively explored." (PMID 31142628, 2019). "RDW was identified as an inflammatory marker in patients with cancer due to its positive association with widely used plasma inflammatory biomarkers such as C-reactive protein (CRP) 43,28,14, erythrocyte sedimentation rate (ESR) 60,47, and interleukin (IL)-6 78 levels." (PMID 31413750, 2019). "In the present study, we found CRP 1846C>T polymorphism was associated with increased risk of LC, which is in consistence with the finding of a meta-analysis showing an increased risk for overall cancer." (PMID 31142628, 2019). "Elevation of CRP is associated with poorer survival in patients with cancer." (PMID 31817109, 2019). "In addition, lesions location, histological types, TNM stage of cancer, smoking, CRP, and APTT were associated with EBB-induced bleeding." (PMID 30658636, 2019). "A host of studies investigated the association between CRP gene polymorphism and cancer risk." (PMID 31142628, 2019). "Other beneficial physiological effects have also been reported along with the positive effects of TAM in the treatment of cancer, including a decrease in circulating cholesterol, dissociation of fibrinogen and C-reactive protein, all of which are recognized as cardiovascular risk factors." (PMID 31249663, 2019). "In addition, CRP has been found to be implicated in the pathogenesis of multiple diseases such as inflammatory diseases, cardiovascular disease, and cancers." (PMID 31915455, 2019). "However, outside of acute stimuli, the year to year, intra-individual variation in CRP is stable with a significant association between baseline CRP and risk of vascular disease and mortality from cardiovascular disease, cancer and respiratory conditions." (PMID 29101476, 2018). "Interestingly, CRP has been proven to be strongly associated with various cancers, exhibiting diagnostic or prognostic value." (PMID 29668751, 2018). "In addition, an association between baseline CRP and early death after diagnosis of any cancer has been reported." (PMID 29954339, 2018).
cancer (continued). "However, replication of trait-associated CpGs across the HM450 and EPIC arrays has been reported for cancer-associated differential methylation, CpGs associated with maternal smoking, C-reactive protein (CRP), and the epigenetic clock." (PMID 30253792, 2018). "This significant association of higher vs. lowest retinol levels with improved survival remained consistent even after adjustment for C-reactive protein, a major inflammatory marker known to be associated with decreased retinol concentrations in cancer patients." (PMID 29671819, 2018). "Finally, our study did not include other parameters, such as D-dimer, fibrinogen, or C-reactive protein, that was found to be associated aTE in cancer patients, for analysis as it was an inherited limitation of our retrospective study." (PMID 30424491, 2018). "However, previously, in 10 studies, the cut-off point of 0.0300-0.6712 was used when examining the association between the CRP/ALB ratio with cancer outcomes in patients with solid cancers." (PMID 29495423, 2018). "The potential mechanisms for the association of CRP with cancer have been proposed." (PMID 28264659, 2017). "A number of studies have revealed that inflammation-based prognostic scores, such as Glasgow prognostic score (GPS), modified Glasgow prognostic score (mGPS), and C-reactive protein and albumin ratio (C/A ratio), are associated with poor outcome in cancer patients." (PMID 28740506, 2017). "Recent studies revealed that CRP was associated with prognosis in several cancers." (PMID 28968977, 2017). "Two meta-analyses investigated CRP gene rs1205 polymorphism with cancer susceptibility previously." (PMID 28706007, 2017). "In particular, the fact that VDR b and T alleles are more frequent in cachectic cancer patients with elevated CRP levels leads to the conclusion that this may represent an early clinical predictor for more aggressive forms of cachexia." (PMID 28423519, 2017). "Furthermore, some studies found that peritoneal infection increased serum interleukin-6 (IL-6), vascular endothelial growth factor (VEGF), and C-reactive protein (CRP) concentrations, which are associated with poor overall and cancer-specific survival." (PMID 27743072, 2017). "Finally, a recent study on cancer patients shows a correlation between the presence of specific VDR BsmI and TaqI alleles and CRP plasma levels, one marker of cancer cachexia." (PMID 28423519, 2017). "Any CRP levels < 10 mg/L were unquantifiable, which may have resulted in an underestimation of the association between serum CRP and these cancers." (PMID 28900475, 2017). "As they are qualitative scores in nature, they may have the potential to cause underestimation (a lower CRP level) or overestimation (a lower albumin level) of the prognostic evaluation in cancer patients." (PMID 28592881, 2017). "In addition, one-unit elevation in pre-RC CRP levels was significantly associated with a 20% increased risk of cancer-related death after RC." (PMID 26880857, 2016). "We hypothesize that combining CRP and leukocyte count would be a robust method of elucidating the associations of biomarkers with cancer risk and mortality." (PMID 26860264, 2016). "The purpose of this study was to test the hypothesis that CRP gene polymorphisms (+942G>C, 1846C>T) modify inherited susceptibility to cancer." (PMID 26912098, 2016). "Increased CRP levels are associated with increased cancer risk." (PMID 27517752, 2016). "In another study among males in 3 large cohorts from the United Kingdom, CRP and leukocyte counts were associated with increased risk of smoking-related cancers but the associations were confounded by smoking such that adjustment for smoking completely attenuated the associations." (PMID 26860264, 2016). "We related CRP concentration and leukocyte count at one-time point to cancer risk and mortality." (PMID 26860264, 2016). "Several lines of work have connected the functional polymorphisms at CRP locus with cancer." (PMID 26912098, 2016).
cancer (continued). "However, the associations between CRP and leukocyte count and cancer risk were attenuated after further adjustment for smoking (model 3)." (PMID 26860264, 2016). "The underling mechanism regarding the elevated CRP level indicating a potential poorer outcome for cancer patients is unknown." (PMID 27733196, 2016). "Our study showed that leptin may be inversely associated with cancer mortality in women, and CRP corresponded with higher risk for cancer death in men." (PMID 26632325, 2016). "Recently, two studies showed that the CRP level correlates with tumor burden in cases of penile cancer.In addition, weight has been thought to be an independent risk factor in patients with cancer." (PMID 26980738, 2016). "As with cancer risk, the further adjustments for smoking attenuated the observed associations between biomarkers and cancer mortality; RR = 1.15 (95 % CI 0.81-1.64, p-trend = 0.43) for CRP, and RR = 1.39 (95 % CI 0.98-1.97, p-trend = 0.42) for leukocyte count." (PMID 26860264, 2016). "Therefore, an ideal way to investigate the role of human CRP gene in cancer susceptibility is to estimate the impact of SNPs within the region on the malignant progression." (PMID 26912098, 2016). "On the other hand, some studies have reported positive associations of CRP and leukocyte count with cancer risk and mortality using the individual markers alone and the reasons may be due to differences in age and gender compositions the study populations." (PMID 26860264, 2016). "Therefore, many inflammatory indicators, including NLR, platelet to lymphocyte ratio, or CRP, are diagnostic and prognostic biomarkers for various cancers." (PMID 26924872, 2016). "In addition, cancer cells can increase the production of inflammatory cytokines, causing increased CRP levels in cancer patients." (PMID 25996920, 2015). "Elevated CRP levels have been linked to shorter survival in several common cancers." (PMID 26717416, 2015). "A combination of high sensitivity C-reactive protein (>3mg/l), albumin and neutrophil count predicted all-cause (HR 7.37, p<0.001, AUC 0.723), cancer (HR 9.32, p<0.001, AUC 0.731), cardiovascular (HR 4.03, p<0.001, AUC 0.650) and cerebrovascular (HR 3.10, p<0.001, AUC 0.623) mortality." (PMID 25730322, 2015). "Several studies proved that supplement of some trophic factors, for example, ω-3 polyunsaturated fatty acids, could improve plasma fatty acid profile, CRP/Alb status, and immune function and prevent weight loss during treatment in cancer patients." (PMID 25934640, 2015). "A consistent association between serum CRP and cancer risk is corroborated by more recent findings, as shown by a metaanalysis of 11 studies in Western populations showing an increased cancer risk for higher levels of CRP." (PMID 26284119, 2015). "Besides being induced in the acute phase of inflammatory response, CRP has been shown to be elevated in patients with a variety of cancer types and an association with prognosis was found." (PMID 26248232, 2015). "However, accumulating evidence has revealed a close association between the serum level of CRP and the risk and prognosis of cancer." (PMID 25025473, 2014). "In this regard, the identification of the highly recurrent CRP-286 SNP mutations in multiple types of human cancer provides a compelling evidence that this protein is a potential driver of tumorigenesis and a core component of the regulatory network of inflammation." (PMID 25025473, 2014). "Interestingly, elevated levels of CRP are associated with increased risk of several types of cancer." (PMID 24782595, 2014). "Prospective studies have shown a higher risk of developing cancer in those with elevated serum CRP." (PMID 24829560, 2014). "Despite the close association of the serum level of CRP with the risk and prognosis of several types of cancer, it remains elusive whether CRP contributes directly to tumorigenesis or just represents a bystander marker." (PMID 25025473, 2014).